NMNAT2 (nicotinamide nucleotide adenylyltransferase 2)
Diseases named in the same sentence as NMNAT2 in open-access papers (continued):
Sharing a sentence is not in itself a finding about the gene and the disease.
neurodegenerative disease (20 papers, 2013 to 2025). A disorder of the central nervous system characterized by gradual and progressive loss of neural tissue and neurologic function. "As NMNAT2 has been implicated as a core component of axon degeneration, if properly tested, these compounds have potential for other neurodegenerative diseases." (PMID 39048544, 2024). "Constitutive NMNAT2 removal results in neurite outgrowth deficits, while knocking down NMNAT2 in developed neurons causes axonal degeneration, a prominent feature of many neurodegenerative diseases." (PMID 27254664, 2016). "NMNAT2 is a newly identified factor for maintaining neuron function, and NMNAT2 expression is positively related to cognitive function and negatively associated with pathological features of neurodegenerative diseases." (PMID 37208728, 2023). "NMNAT2 has a notable impact on diverse medical conditions, encompassing neurodegenerative diseases and malignant tumors." (PMID 38275737, 2024). "Apart from its crucial protective role in neurodegenerative diseases, NMNAT2 exhibits high expression in various solid tumors, playing a significant role in tumor occurrence and progression." (PMID 38275737, 2024). "NMNAT2 targeting small molecules are ideal opportunities for clinical translation in neurodegenerative diseases and aging." (PMID 39048544, 2024). "Inspired by these findings, we analyzed the expression levels of genes in the NAD+ biosynthesis pathways in aging and neurodegenerative diseases and found that NMNAT2, previously documented to be enriched in the cytoplasm, was mainly expressed in the brain." (PMID 34758883, 2021). "The prominent pathology is axon degeneration in many neurodegenerative diseases, while the survival and growth of axons requires nicotinamide mononucleotide adenylyl transferase 2 (NMNAT2), Furthermore, the levels of NMNAT2 are significantly decreased in AD." (PMID 29495349, 2018). "We found that in humans, levels of NMNAT2 transcript are positively correlated with cognitive function and are negatively correlated with pathological features of neurodegenerative disease like plaques and tangles." (PMID 27254664, 2016). "Modulation of the subcellular localization of the endogenous axon survival factor Nmnat2 boosts its axon protective capacity, suggesting a novel approach to delaying axon degeneration in neurodegenerative disease." (PMID 23610559, 2013). "The discovery of these NMNAT2 abundance activators may serve as potential therapeutic agents to restore NMNAT2 levels and ameliorate symptoms in neurodegenerative diseases." (PMID 41009660, 2025). "Interestingly, NMNAT2 abundance seems to be negatively correlated with neurodegenerative stresses, as NMNAT2 mRNA levels are decreased in various neurodegenerative diseases." (PMID 41009660, 2025). "NMNAT2 is reduced in the brains of Alzheimer’s and other neurodegenerative diseases." (PMID 38256175, 2024). "This class of NMNAT2 targeted small molecules could have an important therapeutic impact for neurodegenerative disease following further drug development." (PMID 39048544, 2024). "This could be relevant in many neurodegenerative diseases in which a depletion of NAD generating capacity or NMNAT2 levels have been demonstrated." (PMID 39048544, 2024). "Notably, upregulating NMNAT2 and other NMNATs is protective in multiple neurodegenerative disease models." (PMID 37292715, 2023). "In short, EPB41L4A-AS1 could regulate NAD+ and ATP synthesis by impacting the expression of genes associated with the electron transport chain and NAD+ synthesis pathway (NMNAT2), thus playing an important role in brain aging and neurodegenerative diseases." (PMID 34758883, 2021). "It has been hypothesized that such mutations, affecting the enzymatic activity of NMNAT2 or SARM1, could be considered risk factors for neurodegenerative diseases (Coleman and Höke, 2020)." (PMID 34307460, 2021).
neurodegenerative disease (continued). "Its partial loss may therefore promote neurodegeneration in AD and other neurodegenerative diseases, whereas increased levels of NMNAT2 may protect against the demise of neurons." (PMID 27254664, 2016). "Significance: Modulation of NMNAT2 subcellular localization could delay axon degeneration in neurodegenerative disease." (PMID 25271157, 2014). "Additionally, a drop in the supply of NMNAT2 from neuronal cell bodies into axons could contribute to axon degeneration in neurodegenerative diseases, where axonal transport has been shown to be impaired at an early stage." (PMID 25271157, 2014). "Furthermore, axonal degeneration, a precursor to numerous neurodegenerative diseases, is closely linked to a rapid decline in NAD+ levels, attributed to decreased expression of the NAD+ biosynthetic enzyme nicotinamide mononucleotide adenylyl transferase 2 (NMNAT2)." (PMID 40276601, 2025). "For example, NMNAT2, which is critical for NAD salvage synthesis, has been reported to be downregulated in several neurodegenerative diseases." (PMID 37253984, 2024). "Decreased levels of NMNAT2, triggered by physical injury or pathological stimuli, activate SARM1, leading to axonal degeneration and the onset of neurodegenerative diseases and peripheral neuropathy." (PMID 38275737, 2024). "The suppression of NMNAT2 skews the homeostatic balance that is maintained by the NMNAT2–NAD+–SARM1 axis and results in axonal degeneration, an effect that is commonly observed in many neurodegenerative diseases or as a physiological response to nerve injury (Wallerian degeneration)." (PMID 38396769, 2024).
cancer (13 papers, 2016 to 2025). A tumor composed of atypical neoplastic, often pleomorphic cells that invade other tissues. "Curiously, high levels of NMNAT2 are associated with increased metabolic activity in cancer cells and correlate with growth rate and prognosis of malignant tumors." (PMID 40955574, 2025). "Dysregulations of both NMNAT1 and NMNAT2 have been implicated in cancer." (PMID 34919052, 2021). "Although further studies are needed to identify the molecular mechanisms underlying this transcriptional relationship, our data suggest that maintaining the NMNAT2/SARM1 balance is crucial for cancer cells homeostasis and tumor biology." (PMID 40955574, 2025). "A key finding of the present study is that cancer cell lines expressing SARM1 also exhibit high levels of NMNAT2." (PMID 40955574, 2025). "This dependence on NMNAT2 creates a vulnerability that can be targeted to inhibit cancer cell growth." (PMID 39272943, 2024). "The involvement of NMNAT2 in tumor development and progression has been highlighted in several cancer types." (PMID 38396769, 2024). "This extensively and immediately depletes NAD, impairs glycolysis, prompts energy failure, and ultimately kills NMNAT2-proficient cancer cells by necrosis." (PMID 34068917, 2021). "Future work is required to identify the specific roles of NMNAT1 and NMNAT2 in different cancer types." (PMID 34919052, 2021). "Because of the selective toxicity of Vacor in cancer cells expressing NMNAT2, we originally hypothesized this enzyme is a prerequisite to exert such an antitumor activity." (PMID 40955574, 2025). "On the other hand, given the antitumor potential of Vacor‐like molecules, it is important to clarify whether SARM1 plays a role in cancer cells and to define the role of NMNAT2 in SARM1‐dependent Vacor‐induced cell death." (PMID 40955574, 2025). "Deletion of NMNAT2 leads to protein aggregation, consequently reducing the growth of cancer cells." (PMID 38275737, 2024). "In colorectal cancer, NMNAT2 upregulation correlates with the cancer invasive depth and TNM stage." (PMID 34919052, 2021). "It was recently shown to have cytotoxic activity against NMNAT2-expressing cancer cells." (PMID 34068917, 2021). "Taken together, amplification of Nmnat2 in cancer cells could be a unique target for these compounds." (PMID 30631755, 2018). "Although the exact role(s) of NMNAT2 have yet to be fully elucidated, there is considerable evidence that it may promote cancer cell survival by accelerating glycolysis via a mechanism that includes a reduction in the expression of the transcriptional regulator sirtuin SIRT6." (PMID 33711921, 2021). "However, the role and mechanism of the NAD+ and NMNAT2 in cancer progression is poorly understood." (PMID 33392072, 2020). "Data suggest that the correlation between NMNAT2 and SARM1 expression levels observed in mammalian axons also occurs in cancer cells." (PMID 40955574, 2025). "Other NMNAT2 abundance inhibitors, including bendamustine hydrochloride, retinoic acid, and PAC-1, are chemotherapy drugs used to treat cancers." (PMID 41009660, 2025). "Further, we report that cancer cells sense the abnormal expression of SARM1 and readily induce the expression of NMNAT2." (PMID 40955574, 2025). "Based on these considerations, this study aimed to investigate the contribution of NMNAT2 and SARM1 to Vacor‐induced NAD depletion and cell death in cancer cell lines." (PMID 40955574, 2025). "In other words, NMNAT2 expression could negatively regulate SARM1 activation via modulation of NAD metabolism, thereby creating a feedback loop also in cancer cells." (PMID 40955574, 2025).
cancer (continued). "Interestingly, Vacor is shown to quickly deplete NAD+ and trigger necrosis in cancer cells by inhibiting NAMPT, NMNAT2, and NAD+-dependent dehydrogenases." (PMID 41009660, 2025). "Whether a similar functional interaction between NMNAT2 and SARM1 exists in cancer cells remains unknown." (PMID 40955574, 2025). "Consistently, NMNAT2 overexpression does not sensitize cancer cells to Vacor toxicity." (PMID 40955574, 2025). "We now report, in contrast with our prior hypothesis, that silencing of NMNAT2 in Vacor‐sensitive cancer cell lines neither reduces NAD depletion nor protects from the compound's cytotoxic effect." (PMID 40955574, 2025).
tumor (9 papers, 2016 to 2025). "Specifically, NMNAT2 levels increase in colorectal cancer, showing a positive correlation with tumor invasiveness and stage." (PMID 38275737, 2024). "Compared with ubiquitously expressed NMNAT1 and NMNAT3, NMNAT2 mRNA was reported to be mainly expressed in high energy consumption tissues such as brain, heart, skeletal muscle, and some tumor tissues." (PMID 27218101, 2016). "Compared with patients within TNM stage I/II, NMNAT2-positive tumor tissues were more observed in TNM stage III/IV patients." (PMID 27218101, 2016). "However, the expression of NMNAT2 in CRC tissues was in correlation with the invasive depth of tumor and TNM stage (P < 0.05)." (PMID 27218101, 2016). "In addition, we found that the expression of NMNAT2 protein in tumor tissues had a significant correlation with the invasive depth of tumor and TNM stages according to the statistics (P < 0.05)." (PMID 27218101, 2016). "In addition, acetylation of nicotinamide mononucleotide adenylyltransferase 2 (NMNAT2), decreased Tam-induced apoptosis and/or increased Ku70-Bax interaction may also contribute to the tumor promoter role of SIRT3." (PMID 27483432, 2016). "In this scenario, we previously identified Vacor as a tumor antimetabolite toxified to VAD via NAMPT and NMNAT2, and able to prompt rapid and complete NAD depletion." (PMID 40955574, 2025). "Other genes were modulated in a different way in all three SCCs (NMNAT1, NMNAT2, NADSYN1, SIRT3, and CD38) or in two tumor types (NNMT, NMNAT3, ENPP2, PNP, and SIRT1)." (PMID 38254798, 2024). "Our data showed that NMNAT2 was significantly upregulated in CRC tissues compared with adjacent normal tissues and was correlated with the invasive depth of tumor and TNM stage." (PMID 27218101, 2016). "We claim that understanding the correlation between NMNAT2 and SARM1 activity could have important therapeutic implications and represent a biomarker of tumor aggressiveness." (PMID 40955574, 2025). "The antitumor activity of Vacor was exclusively limited to NMNAT2-expressing tumors, while tumor cell lines that showed no NMNAT2 expression were entirely resistant to Vacor." (PMID 38396769, 2024). "The ROS1-specific overexpression of NMNAT2, an enzyme involved in nicotinamide adenine dinucleotide (NAD) synthesis, and ISL1, a crucial transcription factor regulating glycolysis and tumorigenesis, highlight the metabolic dependencies of ROS1+ tumor specimens and cell lines." (PMID 39737401, 2024).
peripheral neuropathy (6 papers, 2016 to 2024). A disorder affecting the peripheral nervous system. "A recent study illustrated that peripheral neuropathy caused by the chemotherapeutic agents vincristine and bortezomib is also triggered through axonal NMNAT2 depletion and that the consequent NAD+ loss is induced through SARM1 activation." (PMID 38396769, 2024). "As patients with compound heterozygous variants in NMNAT2 exhibit a chronic, motor-predominant peripheral neuropathy, we searched for similar phenotypes in the Nmnat2V98M/R232Q mice." (PMID 36287209, 2022). "Interestingly, 2 sisters homozygous for a different NMNAT2 variant (T94M) — one that largely retains enzymatic activity — also display peripheral neuropathy, albeit significantly milder than the patients described in this study." (PMID 36287209, 2022). "A potential mechanism by which these microtubule-targeting drugs cause peripheral neuropathy could be a reduced supply of NMNAT2 into distal axons." (PMID 26808812, 2016). "Future studies employing a conditional knockout of NMNAT2 or associated proteins may be required to fully elucidate any impact of NMNAT2 on chemotherapy-induced peripheral neuropathy." (PMID 26808812, 2016). "Consequently, depletion of NMNAT2 could be implicated in peripheral neuropathies where synaptic loss is prevalent." (PMID 26808812, 2016). "The failure to detect changes in chemotherapy-induced peripheral neuropathy in adult NMNAT2+/- mice cannot be attributed to compensatory changes in other NMNAT isoforms, NMNAT enzyme activity or changes in MAP2 or neurofilament levels in adult DRG." (PMID 26808812, 2016). "We therefore compared the impact of NMNAT2 knockdown on the development and maintenance of chemotherapy-induced peripheral neuropathy induced by vincristine and paclitaxel treatment using NMNAT2+/- and WT mice." (PMID 26808812, 2016). "In line with the notion that skewed NMN/NAD+ can cause peripheral neuropathy, NAMPT inhibition using the novel agent A4276 was found to protect against Wallerian degeneration (during which NMNAT2 is downregulated) and peripheral neuropathy induced by vincristine and paclitaxel." (PMID 38396769, 2024). "NMNAT2 also protects against chemotherapy-induced peripheral neuropathy." (PMID 38396769, 2024). "For example, reduced transport of NMNAT2 may increase distal axon sensitivity to degeneration due to decreased NMNAT2 levels and is considered common to many peripheral neuropathies." (PMID 35456037, 2022). "Our in vitro studies provide only partial support for this hypothesis whereas our in vivo studies fail to support a protective role for NMNAT2 in chemotherapy-induced peripheral neuropathy." (PMID 26808812, 2016). "Thus, compensatory changes in other NMNAT isoforms or NMNAT enzyme activity are unlikely to account for our failure to observe alterations in chemotherapy-induced peripheral neuropathy in NMNAT2+/- mice." (PMID 26808812, 2016). "Given its indispensable role in axonal and neuronal maintenance, we hypothesized that NMNAT2 depletion may impact the severity of chemotherapy-induced peripheral neuropathies." (PMID 26808812, 2016). "We hypothesized that depletion of NMNAT2 would exacerbate both neurotoxicity and peripheral neuropathy induced by chemotherapeutic treatment." (PMID 26808812, 2016). "To ascertain whether floor effects could contribute to our failure to observe behavioral differences between NMNAT2+/- and WT mice in either the development or maintenance of chemotherapy-induced peripheral neuropathy, we challenged mice of both genotypes with an intradermal injection of capsaicin." (PMID 26808812, 2016). "However, contrary to the in vitro findings, in vivo studies do not provide evidence for NMNAT2’s protective role in chemotherapy-induced peripheral neuropathy." (PMID 38275737, 2024).
neurological disorders (5 papers, 2016 to 2022). "However, whole-exome sequencing performed from patient's blood revealed 12 potentially disease-causative heterozygous variants, amongst which several have been associated with neurological disorders in vitro and in vivo - in particular the axon degeneration-related NMNAT2 gene." (PMID 28035283, 2016). "Nicotinamide mononucleotide adenylyl transferase 2 (NMNAT2) is a key neuronal maintenance factor and provides potent neuroprotection in numerous preclinical models of neurological disorders." (PMID 28266613, 2017). "Whether further mutations to NMNAT2, SARM1 or other proteins involved in the Wallerian degeneration pathway represent risk factors for other neurological diseases in living humans, is yet to be seen." (PMID 34307460, 2021).
adenocarcinoma (1 paper, 2018). A common cancer characterized by the presence of malignant glandular cells. "Next the LIMMA analysis of six Y73SV(+) and four Y73SV(−) adenocarcinoma specimens identified one up-regulated gene, MARCH3, and three down-regulated genes, NMNAT2, ANKRD29, and QSER1, in Y73SV(+) specimens." (PMID 30134863, 2018).
neurodevelopmental disorder (1 paper, 2025). A behavioral and cognitive disorder with onset during the developmental period that involves impaired or aberrant development of intellectual, motor, or social functions. "Among the DEGs, strong evidence of involvement in neurodevelopmental disorders was reported for 15 of them (“definitive” gene list from SysNDD, e.g., PLP1, RGS6, and SCN3A) and moderate evidence for 10 more (“limited” gene list from SysNDD, e.g., UNC13A, NMNAT2, and CHL1)." (PMID 40182141, 2025).
NMNAT2 also shares sentences with these, for which no sentence is quoted: cognitive decline (2 papers); Parkinson’s (2); acute myeloid leukemia (1); amyotrophic lateral sclerosis (1); Blindness (1); breast carcinoma (1); Cognitive impairment (1); frontotemporal dementia (1); granulocytopenia (1); hepatocellular carcinoma (1); hereditary angioedema (1); hereditary spastic paraplegia (1); infection (1); invasive breast carcinoma (1); Leber congenital amaurosis (1); Leber congenital amaurosis 9 (1); lupus (1); lupus nephritis (1); Motor axonal neuropathy (1); motor neuron disorder (1); Obesity (1); optic neuropathies (1); peripheral nerve diseases (1); spinocerebellar ataxia type 1 (1); Stroke (1); triple-negative breast carcinoma (1).